INS (insulin)
Diseases named in the same sentence as INS in open-access papers (continued):
Sharing a sentence is not in itself a finding about the gene and the disease.
ovarian carcinoma (49 papers, 2005 to 2026). A malignant neoplasm originating from the surface ovarian epithelium. "Specifically, we examined ovarian cancer, known for its aggressive behavior associated with insulin signaling dysfunction." (PMID 38272982, 2024). "This study is a Bidirectional Mendelian Randomization Study, which used MR to analyze the two-way causal relationship between insulin related traits and the risk of ovarian cancer." (PMID 36936171, 2023). "In this paper, bidirectional mendelian randomization analysis was used to confirm the causal relationship between insulin related characteristics and ovarian cancer risk." (PMID 36936171, 2023). "The impairment of the insulin secretion rate has a causal effect on the risk of ovarian cancer, which was confirmed by Mendel randomization." (PMID 36936171, 2023). "We found that the insulin secretion rate has a two-way causal relationship with ovarian cancer, which is rarely reported." (PMID 36936171, 2023). "Impaired insulin secretion is often associated with high body mass index, and a large number of statistics have proved the association between overweight and ovarian cancer." (PMID 36936171, 2023). "The summary random effect estimates ranged from 0.18 (95% confidence interval 0.12 to 0.25) for an association between metformin use and ovarian cancer occurrence up to 92.22 (− 73.15 to 257.59) for an association between insulin analogue use and birth weight." (PMID 37072764, 2023). "On the other hand, a randomized controlled trial on 73 endometrial and ovarian cancer patients showed a selective loss of fat mass together with a reduced serum insulin level and retention of lean body mass after 12 weeks of KD." (PMID 36139562, 2022). "Obesity is a risk factor for ovarian cancer and the ketogenic diet was shown to reduce central obesity and reduce insulin levels in ovarian cancer patients." (PMID 33794773, 2021). "Although there is no experimental evidence for the positive association between insulin and ovarian cancer, some studies have shown that the increased serum levels of IGF-1, IGF-1R, and IGFBP-2 were associated positively in patients with ovarian cancer." (PMID 25866823, 2015). "By analyzing the MR results in this paper, we could easily find that impaired insulin secretion was associated with an increased incidence of ovarian cancer." (PMID 36936171, 2023). "In addition to the estrogen-related pathway, dietary fiber is believed to reduce glycemic load and improve insulin sensitivity, thus influence insulin-like growth factors which are suggested to be risk factor for ovarian cancer." (PMID 30376840, 2018). "It is possible that our inability to detect a relationship between sugar intake, ovarian cancer, and insulin modifiers may be a result of variations in risk across subtypes, which we were not able to evaluate due to limited statistical power." (PMID 23442818, 2013). "Accordingly, we propose that ULK2 suppresses the migration and growth of ovarian cancer cells through inhibition of the IGFBP3-mediated insulin signaling pathway." (PMID 38952983, 2024). "Specifically, we examined ovarian cancer, along with glioblastoma and renal cancer, which have received comparatively less attention in the context of insulin signaling dysfunction." (PMID 38272982, 2024). "Insulin can induce apoptosis in ovarian cancer cells through cell cycle regulation and influence inflammation and immune response." (PMID 38166541, 2024). "In summary, our current research exploratively discovered that ULK2 suppressed cell migration and invasion of ovarian cancer via inhibition of the insulin signaling pathway by promoting upregulation of IGFBP3." (PMID 38952983, 2024). "RNA sequencing analysis revealed a potential regulatory role of ULK2 in the insulin signaling pathway through upregulation of insulin-like growth factor binding protein-3 (IGFBP3) in ovarian cancer cells." (PMID 38952983, 2024).
ovarian carcinoma (continued). "Six insulin related indicators, including Fasting blood insulin, Fasting blood insulin adjusted for BMI, Insulin secret rate, Peak insulin response, Acute insulin response and Insulin disposition index, went Two-sample bidirectional MR with ovarian cancer." (PMID 36936171, 2023). "At the same time, another study showed that the existence of ovarian cancer was related to insulin secretion." (PMID 36936171, 2023). "Metabolomic profiling of ovarian cancer ascites has revealed significant differences in the pathways of fatty acids, cholesterol, glucose, and insulin." (PMID 38203494, 2023). "Mendelian randomization (MR) was used to analyze the bidirectional relationship between insulin related characteristics and ovarian cancer." (PMID 36936171, 2023). "This suggests that the human glucose metabolism cycle represented by insulin secretion plays an important role in the pathogenesis of ovarian cancer, which provides a new idea for preventing the release of ovarian cancer." (PMID 36936171, 2023). "This review focuses on the cholesterol and insulin pathways in ovarian cancer, identifying statins and metformin as viable treatment options when combined with standard chemotherapy." (PMID 38203494, 2023). "For example, these cells include oligodendrocytes, insulin-secreting cells, hippocampus, neurons, Jurkat T cells, HeLa cells, and ovarian cancer cells." (PMID 37372630, 2023). "First, from the perspective of insulin and tumor cell energetics, compared with healthy cells, ovarian cancer tumor cells have a huge energy demand to support the abnormal proliferation and metastasis of tumors." (PMID 36936171, 2023). "In the present study, the results were similar to those of a previous report, in which ovarian cancer was less likely to occur in metformin(+)/insulin(+) users (n = 24,033) than in metformin(−)/insulin(−) users (n = 14,853)." (PMID 32825834, 2020). "Most DM patients (74%) were taking oral diabetic therapy at the time of ovarian cancer diagnosis; 2 patients (7%) were using insulin." (PMID 33552546, 2020). "Nevertheless, insulin pathway is also associated with ovarian diseases, such as PCOS, abnormal steroidogenesis, and ovarian cancer." (PMID 31412686, 2019). "The time-dependent re-absorption of Alexa Fluor 488-labeled CA125 by ovarian cancer cells (OVCAR-3) under the high-glucose plus insulin condition." (PMID 29716620, 2018). "Previous works have clarified that the survival, division and proliferation abilities of ovarian cancer cells are all affected by circulating insulin levels." (PMID 29716620, 2018). "Mechanistically, lncRNA promotes the malignant activities of ovarian cancer cells via cancer-related pathways and insulin secretion." (PMID 28969062, 2017). "Our results indicate the differential effects of aging and diet mediated by insulin signaling on the stem cell division cycle, highlight the complexity of the regulation of stem cell aging, and describe a link between ovarian cancer and aging." (PMID 25470527, 2015). "Recently, an alternative therapeutical approach using insulin sensitizers, such as metformin, has been suggested against ovarian cancer." (PMID 22927847, 2012). "Clearly more investigative efforts are needed to confirm the role of this hormone in ovarian cancer although biological evidence suggests a mitogenic role of insulin and IGF-I in the development of this disease." (PMID 20069126, 2010). "In the last couple of years, studies targeting IGF or insulin pathways in ovarian cancer mostly used small molecule IGF-IR kinase inhibitors." (PMID 20069126, 2010). "In this paper, we intend to review the role of insulin/IGF pathway in ovarian cancer and the various strategies to target it." (PMID 20069126, 2010). "These initial studies opened the door to a widespread area of research in ovarian cancer, indicating an involvement of the insulin/IGF system in ovarian tumorigenesis." (PMID 20069126, 2010).
ovarian carcinoma (continued). "In this paper, we will focus on the role of insulin/IGF in ovarian cancer tumorigenesis and treatment." (PMID 20069126, 2010). "For ovarian cancer, metabolic changes such as high insulin and leptin levels may trigger cancer through pathways like PI3K/AKT/mTOR and weaken immune responses." (PMID 41189943, 2025). "Notably, we observed that ovarian cancer down-regulated genes were less affected by decreased NAE1 levels, implicating neddylation in insulin signaling with potential implications for poor prognosis in ovarian cancer patients." (PMID 38272982, 2024). "We will analyze the influence of insulin secretion on ovarian cancer from the following aspects." (PMID 36936171, 2023). "According to the year of the outbreak from far to near, the order was “activated protein kinase”, “ppar alpha”, “arachidonic acid”, “postmenopausal women”, “ovarian cancer”, “in vivo”, “nuclear receptor”, “abnormal lipid metabolism”, “insulin resistance” and “prognosis”." (PMID 37179822, 2023). "In addition to estrogen-related pathways, dietary fiber is thought to reduce glycemic load and improve insulin sensitivity, thereby affecting insulin-like growth factor (IGF), which is considered a risk factor for ovarian cancer." (PMID 37299507, 2023). "Ovarian cancer xenograft animal and cancer cell models were used to recapitulate the clinical findings and reveal the molecular basis of postprandial blood glucose and insulin in invoking the synthesis/secretion/re-absorption of CA125." (PMID 29716620, 2018). "Too much HNF1B is associated with apoptosis and a decrease in insulin secretion whilst lack of expression is known to cause hyper proliferation and is associated with clear-cell and ovarian carcinomas." (PMID 19787084, 2008). "However, all three ovarian cancer cell lines recovered following ARG/insulin treatment." (PMID 38374190, 2024). "Similar results have been observed also in women with endometrial or ovarian cancer that underwent KD or a diet high in fiber and low in fat: change in visceral fat depots was grater in the KD group with retention of the lean mass and decrease of serum fasting insulin." (PMID 34205356, 2021). "Similarly, increased insulin signaling due to elevated circulating insulin levels contributes to enhanced tumor growth, which along with hyperglycemic effects on tumor cells, suggests enhanced metabolism as a contributing factor to ovarian cancer progression." (PMID 27533079, 2016). "However, some incidences in which the ovary displays insulin sensitivity and steroidogenesis induced by insulin and IGFs suggest that T2DM may be an important risk factor for ovarian cancer." (PMID 25866823, 2015). "Moreover, over the last decade, accumulating data suggest that the insulin/IGF pathway might be a promising therapeutic target in ovarian cancer." (PMID 22927847, 2012). "However, the role of insulin/IGF in ovarian cancer warrants further description." (PMID 20069126, 2010). "We investigated and compared the effects of ARG and insulin treatment to ARG treatment alone in three different cancer types, namely breast, lung and ovarian cancer." (PMID 38374190, 2024). "Insulin, GIP, and PP were only measured in the NHL and ovarian cancer studies; Spearman correlation coefficients were calculated for the three markers by study." (PMID 28753646, 2017). "Indirect effects of AMPK results in attenuation of the insulin/IGF-1 pathways, which are known to be upregulated in many cancers including ovarian cancer." (PMID 25895126, 2015). "In a previous study, we showed that a high energy diet (HED) was associated with extensive ovarian tumor formation, elevation of insulin, insulin growth factor (IGF-1) and higher levels of inflammation markers in an isogeneic mouse model of ovarian cancer." (PMID 25895126, 2015). "Primary ovarian cancer cells were dissociated and placed in uncoated culture flasks in serum-free medium supplemented with EGF, b-FGF, insulin, and BSA." (PMID 25369529, 2014).
ovarian carcinoma (continued). "By conjugating His-tagged-NEDD8 in SKOV3 ovarian cancer cells with and without insulin treatment, we identified differentially expressed proteins (DEPs) in the PC vs His-NEDD8 and PC vs His-NEDD8+insulin comparisons." (PMID 38272982, 2024). "We also analyzed the serum and ascites levels of insulin and IGF-1 in mice with ovarian cancer." (PMID 29844867, 2018). "Insulin and PP were weakly correlated (0.2 for the NHL and ovarian cancer studies); however, GIP was moderately correlated with insulin (0.5 for the NHL and ovarian cancer studies) and weakly correlated with PP (0.3 for the NHL study and 0.4 for the ovarian cancer study)." (PMID 28753646, 2017). "Extracellular signals that induce VEGF-A through this proximal region include, among others, growth factors such as EGF, insulin and PDGF in fibroblasts, prostaglandin E2 in human muscle cells, M-CSF in monocytes and lysophosphatidic acid (LPA) in ovarian cancer cells." (PMID 23506169, 2013). "Over the last decade, accumulating data suggest that the insulin/IGF pathway might be one such good therapeutic target in cancers, including ovarian cancer." (PMID 20069126, 2010). "Evidence accumulates suggesting that the insulin/insulin growth factor (IGF) pathways could act as a good therapeutic target in several cancers, including ovarian cancer." (PMID 20069126, 2010). "However, it should be noted that many studies have pointed out that the postmenopausal serum insulin level is not related or is very weak to ovarian cancer after adjustment and correction, which is consistent with the negative results of this study." (PMID 36936171, 2023). "We then performed an immunoassay to assess whether or not these dietary manipulations could modulate the insulin/IGF production in ovarian cancer." (PMID 29844867, 2018).
angina (48 papers, 2010 to 2025). "We have also reported that the infusion of insulin in the AMI victims favourably reduced the anginal pain including unstable angina." (PMID 24558405, 2014). "Nicorandil, a KCO used as a human angina treatment, decreases glucose metabolism, causing insulin resistance without interfering with insulin secretion." (PMID 38612888, 2024). "Conversely, less limited living conditions that enable higher levels of insulin, with corresponding effects acting on MI and angina via male reproductive factors may explain the higher rates of CVD in men than women that emerge with economic development." (PMID 31508506, 2019). "Genetically predicted insulin was associated with MI (odds ratio (OR) 4.27 per pmol/L higher insulin, 95% confidence interval (CI) 1.60 to 11.3) and angina (OR 2.93, 1.27 to 6.73) in men, but not women (MI OR 0.80, 95% CI 0.23 to 2.84, angina OR 1.10, 95% CI 0.38 to 3.18)." (PMID 31508506, 2019). "They find an association of insulin with MI and angina in men but not women, which may contribute to the different rates of cardiovascular diseases in men and women." (PMID 31508506, 2019). "The proportion of current tobacco smokers, users of insulin, and those with a history of NSTEMI and angina were significantly higher in participants with significant CAD compared to those without significant CAD." (PMID 37868128, 2023). "In patients with unstable angina, we discovered that activation of immune-inflammatory pathways (CRP and cytokines including IL-6) affects the physio-affective phenome of unstable angina, and that these effects are mediated by increased atherogenicity and insulin resistance." (PMID 36011997, 2022). "In conclusion, OGTT 2 h insulin level and metabolic unhealthiness were found to be useful diagnostic parameters for differentiating between CAD and CSX in subjects with angina pectoris undergoing CAG but without known DM, whereas fasting IR or HbA1C indices were not." (PMID 28194232, 2017). "The main finding of our study was that higher OGTT 2 h insulin level and being metabolically unhealthy were useful indices for differentiating between CAD and CSX in subjects undergoing CAG for angina pectoris but without known DM history." (PMID 28194232, 2017). "Post challenge OGTT 2 h insulin and being metabolic unhealthy were useful parameters in differentiating between CAD and CSX in subjects without known DM but suffered from angina pectoris and underwent CAG." (PMID 28194232, 2017).